BIRC7 (baculoviral IAP repeat containing 7)
Diseases named in the same sentence as BIRC7 in open-access papers:
BIRC7 is named in the same sentence as 26 diseases in open-access papers, as found by Europe PMC text mining. Sharing a sentence is not in itself a finding about the gene and the disease. The quoted sentences say what the papers report.
melanoma (31 papers, 2007 to 2025). A malignant, usually aggressive tumor composed of atypical, neoplastic melanocytes. "Module M2 contained the STAT1 regulator, which has been linked to C4 Melanoma CORO1A, C0 Melanoma BIRC7, and C6 Melanoma GJB2." (PMID 37435067, 2023). "It has been shown that the virus can induce apoptosis in melanoma cultures overexpressing a protein called Livin, encoded by the BIRC7 gene." (PMID 33322507, 2020). "A total of 10137 melanoma cells were further grouped into seven subtypes, i.e., C0 Melanoma BIRC7, C1 Melanoma CDH19, C2 Melanoma EDNRB, C3 Melanoma BIRC5, C4 Melanoma CORO1A, C5 Melanoma MAGEA4, and C6 Melanoma GJB2." (PMID 37435067, 2023). "A total of 10137 melanoma cells were clustered into 7 subtypes (C0 Melanoma BIRC7, C1 Melanoma CDH19, C2 Melanoma EDNRB, C3 Melanoma BIRC5, C4 Melanoma CORO1A, C5 Melanoma MAGEA4, C6 Melanoma GJB2)." (PMID 37435067, 2023). "Module M4 contained regulators such as FOSL1 that are associated with C1 melanoma CDH19 and C0 melanoma BIRC7." (PMID 37435067, 2023). "It is a positive regulator of the anti-apoptotic gene BCL2 (BCL2 apoptosis regulator) both in normal melanocytes and in human cutaneous melanoma cells, and of BIRC7 (baculoviral IAP repeat containing 7) in melanoma cells." (PMID 35682684, 2022). "On the contrary, BIRC7, a member of the inhibitor of the apoptosis protein family, was reported to protect melanoma cells against NK cell-induced apoptosis." (PMID 35370464, 2022). "Livin/BIRC7 was first identified in melanoma and consists of a single BIR domain that is homologous to the BIR3 domain of others IAPs, and a RING (Really Interesting New Gene) Zink finger domain." (PMID 28030838, 2017). "SWI/SNF can promote melanoma survival by remodeling the IAP promoter leading to enhanced MITF-driven BIRC7 (Livin/ML-IAP) expression." (PMID 26426052, 2015). "BIRC7 transcription is also directly activated by MITF, and overexpression of BIRC7 rescued melanoma from apoptosis in MITF-depleted melanoma cells." (PMID 22046555, 2011). "Thus far, 8 out of 21 GLI targets we chose to validate—KRT16, S100A9, SOX9, BIRC7, EBI3, FLG, SAMMSON and SPRY2—were already implicated in melanoma pathogenesis." (PMID 36139698, 2022). "BRG1 may be increased during melanoma progression, potentially causing a shift of MITF target genes towards anti-apoptotic signaling via BIRC7/ML-IAP, although conflicting reports exist about BRG1 expression in melanoma progression." (PMID 26426052, 2015). "Notably, elevated levels of this protein are observed in most melanoma cell lines, which may indicate the importance of BIRC7 for the survival of this tumor type." (PMID 41465443, 2025). "Baculoviral IAP repeat containing 7/melanoma inhibitor of apoptosis (BIRC7/ML-IAP), which is an antiapoptotic regulator, is highly expressed in human melanomas and provides resistance to apoptosis-based chemotherapeutic treatments." (PMID 22046555, 2011).
colorectal cancer (4 papers, 2020 to 2021). A primary or metastatic malignant neoplasm that affects the colon or rectum. "Online databases Oncomine and GEPIA were used to compare the expression of IAPs (NAIP, BIRC2, BIRC3, XIAP, BIRC5/survivin, BIRC6 and BIRC7, no data on BIRC8 was available) between colorectal cancer and normal tissues." (PMID 32381104, 2020).
endometrial carcinoma (2 papers, 2021 to 2022). A malignant tumor arising from the epithelium that lines the cavity of the uterine body. "No data were identified concerning the diagnostic or prognostic impacts of livin/BIRC7 gene expression in endometrial hyperplasia and/or endometrial carcinoma." (PMID 34568983, 2021). "Therefore, our findings provided evidence that the detection of livin/BIRC7 may be used as a reliable diagnostic biomolecular technique for endometrial carcinoma." (PMID 34568983, 2021). "In differentiating endometrial carcinoma from endometrial hyperplasia, livin/BIRC7 expression was the most powerful with AUC = 0.94 compared to 0.87 and 0.59 for MDA and catalase respectively." (PMID 34568983, 2021). "Regarding differentiation of endometrial carcinoma from endometrial hyperplasia, the performance of both still great but livin/BIRC7 is superior regarding AUC value and accuracy (0.94 with accuracy of 80% for livin/BIRC7 vs. 0.87 with accuracy of 73% for MDA)." (PMID 34568983, 2021). "The detection of livin/BIRC7 in endometrial carcinoma has excellent sensitivity and specificity." (PMID 34568983, 2021). "Also, they are excellent for differentiation of endometrial carcinoma cases from controls; however, livin/BIRC7 is more powerful than MDA regarding AUC value (0.998 vs. 0.991) with the same accuracy (97%) for the two." (PMID 34568983, 2021). "Moreover, apoptotic markers in endometrial carcinoma should be studied in correlation with livin/BIRC7 gene expression." (PMID 34568983, 2021). "The other study reported higher transcript levels for baculoviral IAP repeat containing 7 (BIRC7), polo-like kinase 1 (PLK1) and multiple cell cycle regulatory proteins in endometrial cancer specimens from Black compared to White patients." (PMID 35887124, 2022). "The ROC curve analysis was applied to assess the power of livin/BIRC7 expression, catalase activity, and MDA levels in discriminating between endometrial carcinoma, hyperplasia, and normal endometria." (PMID 34568983, 2021). "Similarly, livin/BIRC7 expression and MDA were significant (p < 0.001), AUC = 0.998 and 0.991 respectively compared to 0.613 for catalase (p = 0.13) in predicting endometrial carcinoma." (PMID 34568983, 2021). "In the current study, using ROC curve analysis, we found that livin/BIRC7 expression and MDA level but not the catalase could be used as additional dependable parameters in the diagnosis of the suspected cases with endometrial carcinoma and endometrial hyperplasia." (PMID 34568983, 2021).
leukemia (2 papers, 2020 to 2021). A malignant (clonal) hematologic disorder, involving hematopoietic stem cells and characterized by the presence of primitive or atypical myeloid or lymphoid cells in the bone marrow and the blood. "Moreover, this subset also shares leukemia and pro‐B gene expression signatures as well as high levels of the ETV6 target genes (BIRC7, WBP1L, CLIC5, ANGPTL2) with the ER subtype, indicating that these B‐other cases are the recently identified ER‐like subtype." (PMID 33987955, 2021).
lung carcinoma (2 papers, 2014 to 2023). "XIAP (BIRC4), Survivin (BIRC5), Livin (BIRC7), and BRUCE or Apollone ((BIRC6) are four members of the IAP family that play an important role in the development of chemoresistant lung cancer." (PMID 36800962, 2023).
neuroblastoma (2 papers, 2015 to 2020). Neuroblastoma (NB) is the most common solid, extracranial childhood tumor. "BIRC7 is an apoptotic inhibitor whose expression levels are correlated with poor prognosis of neuroblastoma patients." (PMID 25944692, 2015).
renal cell carcinoma (2 papers, 2018 to 2025). "In renal cell carcinoma, down-regulation of CXXC4 by siRNA resulted in the up-regulation of some cellular proliferation related genes (FGF18, EGR1, and MYCN), the down-regulation of apoptosis inhibitor proteins BIRC7 and XAF1, and some other important tumor progression factors." (PMID 30042169, 2018).
breast carcinoma (1 paper, 2021). "In the cited paper, the authors have shown that higher expression of the BIRC5 and BIRC7 genes is associated with higher tumor staging, and higher expression of the BIRC5 gene was associated with worse survival across breast cancers." (PMID 33673050, 2021).
clear cell renal carcinoma (1 paper, 2022). A malignant epithelial neoplasm of the kidney characterized by the presence of lipid-containing clear cells within a vascular network. "The finding that LAMA4, BIRC7, GALNTL6, WNK2, and IGFBP2 are potential targets of miR-217 at different times of tumor evolution may help to develop stage-specific strategies, taking into account the differential expression of miR-217 in each stage of clear cell renal carcinoma progression." (PMID 35936681, 2022).
depressed (1 paper, 2020). "Taken together, MYC might initiate the carcinogenesis of depressed neoplasms at the early stage, and subsequently, CCNA1 and BIRC7 might promote its invasiveness and further migration." (PMID 32532105, 2020).
hepatoblastoma (1 paper, 2024). Hepatoblastoma (HB) is a malignant hepatic tumor and is the most common pediatric liver cancer. "Indeed, mutations in the YTHDF2 were linked to the lower expression of BIRC7 and NK4IN4 in human hepatoblastoma, and genetic duplication of GMBE1 and YTHDF2 was noted in cases of human megalencephaly, suggesting them as candidate genes for this disease." (PMID 39596561, 2024).
lung adenocarcinoma (1 paper, 2026). A carcinoma that arises from the lung and is characterized by the presence of malignant glandular epithelial cells. "Some of these genes (HMGA2, MMP13, BIRC7, and PLA2G2D) have been reported to be overexpressed in various cancers, including lung adenocarcinoma, and are associated with tumor progression and metastasis, supporting their potential as biomarkers for PD-1 immunotherapy." (PMID 41529246, 2026).
Miscarriage (1 paper, 2022). A pregnancy that ends at a stage in which the fetus is incapable of surviving on its own, defined as the spontaneous loss of a fetus before the 22th week of pregnancy. "Considering the decreased level of BIRC7 and slightly increased number of NK cells in the RM group which leads to the occurrence of miscarriage, we attribute that BIRC7 in decidua meconium may possess the ability to prevent NK cells from killing embryonic and extraembryonic cells." (PMID 35370464, 2022).
ovarian carcinoma (1 paper, 2019). A malignant neoplasm originating from the surface ovarian epithelium. "We found that BIRC3 expression correlated inversely with ovarian cancer patient outcome, while BIRC2, BIRC4, BIRC5, and BIRC7 had no significant impact on patient outcome." (PMID 30718461, 2019).
prostate carcinoma (1 paper, 2022). A carcinoma that arises from epithelial cells of the prostate gland. "Baculoviral IAP Repeat Containing 7 (BIRC7) is an inhibitor of apoptosis (IAP) family gene whose expression is linked to tumor progression and metastasis in lung and prostate cancer." (PMID 35846375, 2022).
thyroid cancer (1 paper, 2020). "Among the four methylation-driven genes, the high expression level of TREM1, BIRC7, and SLC26A7 prognosticated low survival rate, whereas RDH5 acted as protective genes to suggest good prognosis of thyroid cancer." (PMID 32296463, 2020).
cancer (22 papers, 2013 to 2026). A tumor composed of atypical neoplastic, often pleomorphic cells that invade other tissues. "An important role in cancers is played by livina—a protein encoded by the BIRC7 (Baculoviral IAP Repeat Containing 5) gene." (PMID 33673050, 2021). "The overexpression of BIRC7 in cancers is reported to be associated with cancer drug and radiotherapy resistance, disease recurrence and poor survival." (PMID 34441816, 2021). "BIRC3 and BIRC7 were the second most predictive genes each associated with tumor stage in five cancer types." (PMID 31964418, 2020). "In addition, EMT-related microRNAs were noted, including miR-218-2, which was frequently repressed and co-methylated with its host gene SLIT3; miR-214, which targets EZH2, β-catenin, and BIRC7 —all were genes implicated in cancer metastasis and invasion; miR-382, which targets ROR1." (PMID 30922328, 2019). "The analysis revealed that several members of the IAP family, including NAIP, BIRC2, BIRC3, XIAP, BIRC5, BIRC6, and BIRC7, exhibited higher expression levels in multiple cancers, including HCC." (PMID 37781078, 2023). "There have been accumulated evidence that overexpression of BIRC7 in cancers has been connected to chemo- and radio-resistance, relapse, and poor survival." (PMID 34568983, 2021). "This case-control study was intended to investigate livin/BIRC7 gene expression in endometrial hyperplasia and carcinoma and its correlation to some oxidative stress markers in addition to its possible diagnostic performance." (PMID 34568983, 2021). "A positive correlation was found between livin/BIRC7 expression and serum catalase activity and malondialdehyde level in endometrial hyperplasia and carcinoma." (PMID 34568983, 2021). "The frequency of apoptosis pathway regulations varied among different IAPs, with BIRC3 and BIRC6 both regulating 36.4% of cancers while BIRC7 only regulating 12.5% of cancers in at least one of the apoptosis pathways (overall proportion test P = 0.0022)." (PMID 31964418, 2020). "Remarkably, BIRC5 (survivin) was significantly overexpressed in 94% of the cancers followed by BIRC7 which was overexpressed in 66% of the cancers." (PMID 31964418, 2020). "The capacity of apoptosis regulations among IAPs also differed with BIRC3 and BIRC6 both regulating 36.4% of cancers while BIRC7 only regulating 12.5% of cancers in at least one of the apoptosis pathways." (PMID 31964418, 2020). "There were sporadic regulations exerted by BIRC7, with the majority of enriched pathways shared by less than one third of the cancers." (PMID 31964418, 2020). "Secondly, since the in vitro cell culture model has been a crucial tool for hypothesis-driven cancer research, we probed the expression of BIRC7/Livin protein in the SW480 CRC cell line by immunoblot." (PMID 33465114, 2021). "Thus, our team was motivated to explore the livin/BIRC7 gene expression in both endometrial hyperplasia and carcinoma, in relation to some oxidative stress markers, and its diagnostic performance to help in developing better treatment strategies." (PMID 34568983, 2021). "To examine the relationship between cancer development and BIRC5 and BIRC7, we compared the expression levels in patients at various stages." (PMID 38203388, 2023). "BIRC7, a novel member of the IAP family, is found to be highly overexpressed in various cancer types." (PMID 34441816, 2021). "Between BIRC5 and BIRC7, both positive and negative correlations were observed across the 32 cancers, demonstrating a histology dependent co-expression pattern." (PMID 31964418, 2020). "Up regulation of several IAPs like NAIP (BIRC1), X-linked IAP (XIAP, BIRC4), Survivin (BIRC5), c-IAP1 (BIRC2), c-IAP2 (BIRC3), Apollon (BRUCE, BIRC6), Livin/MLIAP (BIRC7) and IAP-like protein 2 (BIRC8) have been reported in several cancer cells as well as in serum from cancer patients." (PMID 29464049, 2018). "BIRC7 was found to be overexpressed in 66% of the cancers and to be absent in normal cells/tissues." (PMID 34441816, 2021).
cancer (continued). "Unlike BIRC5 and BIRC7 which demonstrated a strong oncogenic role, BIRC6 tended to function as a tumor suppressor since it was down-regulated in eight human cancers." (PMID 31964418, 2020).
tumor (15 papers, 2010 to 2026). "The mRNA expression of BIRC7 showed significantly higher expression in tumors compared to non-tumor in the three RCC subtypes." (PMID 38203388, 2023). "We then analyzed the mRNA expression of the eight members of the BIRC family and found that only BIRC5 and BIRC7 were overexpressed in tumor tissues." (PMID 38203388, 2023). "We observed that the BIRC2, BIRC3, BIRC5, and BIRC7 genes showed the increased levels of expression in tumor tissue compared to normal tissue, while in the case of the BIRC1, BIRC4, BIRC6, and BIRC8 genes, we saw the decreased expression levels." (PMID 33673050, 2021). "BIRC7/Livin has been reported to facilitate tumour cell metastasis in CRC by evasion of apoptosis and autophagy." (PMID 33465114, 2021). "We used MYC, CCNA1, and BIRC7 in combination as a D-marker panel for identifying depressed neoplasms, and tested the panel in the discovery set." (PMID 32532105, 2020). "CNAs in MYC, CCNA1, and BIRC7 were significantly enriched in depressed neoplasms and designated as the D-marker panel." (PMID 32532105, 2020). "The present study demonstrates that MYC, CCNA1, and BIRC7 alterations are significantly enriched in depressed neoplasms." (PMID 32532105, 2020). "As expected from the SNP-array data, the MYC and BIRC7 relative transcript levels were up-regulated in 15/18 (83%) and 14/18 (78%) tumours analyzed, respectively." (PMID 21060790, 2010). "In our study, increased BIRC7 expression might be a survival mechanism when tumor cells undergo the stimulation of pro-apoptosis agent." (PMID 32231733, 2020). "In our study, we found an upregulation of Survivin/BIRC5 and Livin/BIRC7 in microdissected tumor-tissue and we could validate the dysregulation of Livin/BIRC7 by quantitative RT-PCR and IHC." (PMID 20808857, 2010). "BIRC7 has recently been shown to be upregulated in several validated PTC cell lines, as well as fresh tumor tissue from PTC patients, as compared to wildtype thyrocytes or benign thyroid tissue." (PMID 35846375, 2022). "The sensitivity, specificity, and accuracy of the D-marker panel for discriminating the depressed from the polypoid neoplasms and the arm-level changes in MYC, CCNA1, and BIRC7 in each case in the discovery set were calculated." (PMID 32532105, 2020). "Depressed neoplasms seem to arise via a distinct molecular pathway, in which alterations in MYC, CCNA1, and BIRC7 play a significant role." (PMID 32532105, 2020). "Compared to the NCI60 analysis, we further revealed distinct expression pattern of BIRC5 and BIRC7 and synchronized expression for NAIP, BIRC2, BIRC3, XIAP and BIRC6 in multiple tumor types." (PMID 31964418, 2020).
hematological malignancies (1 paper, 2024). "We found that high expression of SEC61A1 was associated with upregulation of EPHA3, MMP7, BIRC7, and ROS1, all of which have been reported as prognostic markers or therapeutic targets in hematological malignancies." (PMID 38584833, 2024).
BIRC7 also shares sentences with these, for which no sentence is quoted: colon cancer (4 papers); bladder cancer (1); cutaneous melanoma (1); hepatocellular carcinoma (1); infection (1); megalencephaly (1); non-small cell lung carcinoma (1).